NLRP3 (NLR family pyrin domain containing 3)
Diseases named in the same sentence as NLRP3 in open-access papers (continued):
Sharing a sentence is not in itself a finding about the gene and the disease.
chronic obstructive pulmonary disease (continued). "Previous research demonstrated that arginine administration improved pulmonary function in a rat model of chronic obstructive pulmonary disease (COPD) by regulating the ROS/NLRP3/NF-κB signaling pathway and reducing inflammatory mediator levels." (PMID 41346673, 2025). "Accordingly, fructose has been indicated to enhance inflammation that promotes cardiac remodeling and cardiac arrhythmias, and it is expected that targeting fructose-induced NF-κB/NLRP3 inflammasome activation and cytokine secretion might reduce cardiac dysfunction." (PMID 34201938, 2021). "In recent study, the colchicine could reduce the NLRP3 inflammasome activity or its downstream mediators in the cancer related to chronic inflammation diseases such as the hyperlipidemia with atherosclerosis, tobacco use with chronic obstructive pulmonary disease (COPD) and chronic colitis." (PMID 38649928, 2024). "Nucleotide-binding oligomerization domain-like receptor family pyrin domain-containing 3 (NLRP3) inflammasome activation plays an important role in chronic obstructive pulmonary disease (COPD) pathogenesis and might be involved in ongoing chronic inflammation." (PMID 35534521, 2022). "In a mouse model of chronic obstructive pulmonary disease (COPD), dexamethasone not only downregulated NLRP3, caspase-1, and IL-1β but also upregulated the levels of SOD." (PMID 34512868, 2021). "PDE4 inhibitor Roflumilast is FDA-approved for treating severe chronic obstructive pulmonary disease (COPD), but the specific role of PDE10A in NLRP3 inflammasome activation remains unclear." (PMID 40429643, 2025). "The interplay between purinergic receptors as well as pattern recognition receptors like Toll-like receptors (TLRs) and NOD-, LRR-, and pyrin domain-containing protein 3 (NLRP3) might have a role in the pathogenesis of chronic obstructive pulmonary disease (COPD)." (PMID 38811459, 2024). "Therefore, it is conjectured that dysregulated instigation of NLRP3 may influence the advancement of chronic lung diseases such as IPF, asthma, and chronic obstructive pulmonary disease." (PMID 39966334, 2025). "Finally, the robust results obtained here using the NLRP3 inhibitor, MCC-950, open a new therapeutic avenue for T1D induced cardiac arrhythmias, since it improves the cardiac electrical profile, while keeping other inflammasomes involved in the response to infectious diseases intact." (PMID 27882934, 2016).
experimental autoimmune encephalomyelitis (58 papers, 2013 to 2026). An autoimmune demyelinating disease of the central nervous system that is produced experimentally in animals by the injection of homogenized brain or spinal cord in Freund's adjuvant. "Studies have shown that the activation of the NLRP3 inflammasome is closely associated with the severity of myelin damage and neuroinflammation in MS patients and experimental autoimmune encephalomyelitis (EAE) mouse models." (PMID 40552323, 2025). "MCC950 is a small molecule that selectively inhibits the NLRP3 inflammasome and attenuates disease severity in a number of experimental autoinflammatory disease models, including murine experimental autoimmune encephalomyelitis and cryopyrin-associated autoinflammatory syndrome." (PMID 28192528, 2017). "NLRP3 is an intracellular sensor molecule that affects neutrophil functionality and infiltration in brain disorders such as experimental autoimmune encephalomyelitis (EAE)." (PMID 40413505, 2025). "Caffeine inhibited the activation of NLRP3 inflammasome through autophagy to reduce neuroinflammation-mediated by microglia cells in experimental autoimmune encephalomyelitis." (PMID 38808888, 2024). "The activation of the NOD-like receptor family pyrin domain-containing protein 3 (NLRP3) inflammasome triggers pyroptosis proinflammatory cell death in experimental autoimmune encephalomyelitis (EAE)." (PMID 36765034, 2023). "By mediating Th1 and Th17 responses, NLRP3 is critically involved in experimental autoimmune encephalomyelitis." (PMID 37312878, 2023). "In 2012, NLRP3 inflammasome was reported to promote chemotactic immune cell migration to the CNS in experimental autoimmune encephalomyelitis (EAE), an animal model of multiple sclerosis." (PMID 36494392, 2022). "In this study, we demonstrated that manoalide can effectively inhibit the activation of NLRP3 inflammasome and ameliorate the pathogenesis of experimental autoimmune encephalomyelitis in mice." (PMID 35252186, 2022). "Neuroinflammation and demyelination are modulated by NLRP3 and pyroptosis in experimental autoimmune encephalomyelitis model mice." (PMID 36072486, 2022). "LPC can also activate the NLRP3 and NLRC4 inflammasomes in macrophages, microglia and astrocytes, and NLRP3 is reported to be detrimental in experimental autoimmune encephalomyelitis." (PMID 35137954, 2022). "Expression of the Nlrp3 gene increased in the spinal cord during the progression of experimental autoimmune encephalomyelitis (EAE), an animal model of MS, and deletion of the Nlrp3, Casp1, Pycard, or Il1b genes in mice led to resistance to EAE." (PMID 33535473, 2021). "CD39-expressing DCs converted extracellular ATP to ADP and AMP molecules, which were critical to down-regulate NLRP3 inflammasome and protect the host from experimental autoimmune encephalomyelitis (EAE)." (PMID 29033934, 2017). "Recent studies showed that the NLRP3 inflammasome exacerbates experimental autoimmune encephalomyelitis (EAE), an animal model of MS, although EAE can also develop without the NLRP3 inflammasome." (PMID 23365725, 2013). "It is important to recall that the direct involvement of the NLRP3 inflammasome in the onset and development of MS has been demonstrated in the experimental autoimmune encephalomyelitis (EAE) animal model, which justifies the particular relevance of IL-1β in MS." (PMID 37693246, 2023). "Furthermore, NLRP3 is also reported to mediate pyroptosis in other CNS diseases, such as experimental autoimmune encephalomyelitis and neuromyelitis." (PMID 35659106, 2022). "Additionally, a role of the NLRP3 inflammasome has been demonstrated in the development of experimental autoimmune encephalomyelitis (EAE)." (PMID 32563262, 2020). "In experimental autoimmune encephalomyelitis (EAE) improvement of phenotype by Nlrp3 depletion." (PMID 31892810, 2019).
experimental autoimmune encephalomyelitis (continued). "As immune dysfunction is primarily involved in the pathogenesis of MS, this study aimed to explore the therapeutic effects and precise functional mechanisms of ghrelin against the nod-like receptor protein 3 (NLRP3) inflammasome and pyroptosis in experimental autoimmune encephalomyelitis (EAE)." (PMID 31780940, 2019). "Furthermore, NLRP3 expression and NLRP3-mediated IL-1β secretion are increased in RA patients, and NLRP3 is involved in the pathogenesis of experimental autoimmune encephalomyelitis." (PMID 29892303, 2018). "A recent study using an experimental autoimmune encephalomyelitis (EAE) mouse model, a widely accepted model for MS, demonstrated that NLRP3 exacerbated EAE severity through ROS-dependent neutrophil extracellular trap (NET) formation in the brain." (PMID 40242770, 2025). "Some studies in other CNS autoimmune disease such as experimental autoimmune encephalomyelitis (EAE), have demonstrated that NLRP3 inflammasome promotes neuroinflammation by inducing the migration of Th1 and Th17 cell to CNS." (PMID 31214158, 2019). "Interestingly, CD4+ T cells needed to be primed by NLRP3 inflammasome-sufficient antigen-presenting cells to upregulate chemotactic proteins such as osteopontin, CCR2, and CXCR6 in experimental autoimmune encephalomyelitis (EAE)." (PMID 36766797, 2023). "In addition, TRPV1 deletion could alleviate mice experimental autoimmune encephalomyelitis (EAE) and reduce neuroinflammation by inhibiting NLRP3 inflammasome activation." (PMID 34907173, 2021). "As we recently demonstrated the presence of an NLRP3 inflammasome-independent subset in experimental autoimmune encephalomyelitis (EAE), an animal model of MS, the NLRP3 inflammasome may not be involved in the development of all kinds of MS, which is a multifactorial and heterogeneous disease." (PMID 23365725, 2013).
Hepatitis (56 papers, 2013 to 2026). Inflammation of the liver. "This phenotype is closely associated with abnormal activation of the NLRP3 inflammasome, a key driver of hepatitis that initiates inflammatory cascades through Caspase-1-mediated maturation of IL-1β and IL-18." (PMID 40868283, 2025). "In brief, these results demonstrated that caspase-1 was required for IL-1β production in ConA-induced hepatitis and caspase-1 deficiency prevented NLRP3 inflammasome activation and pyroptosis, thus ameliorating liver inflammation and injury." (PMID 29692782, 2018). "Collectively, these results indicated that NLRP3 played a pathogenic role in the pathogenesis of ConA-induced hepatitis through eliciting IL-1β production and pyroptosis." (PMID 29692782, 2018). "Here, we reported that NLRP3 and caspase-1 were required for the activation of IL-1β in a murine model of ConA-induced AIH, and mice deficient in NLRP3 or caspase-1 (NLRP3−/− or caspase-1−/−) were protected from hepatitis." (PMID 29692782, 2018). "Similarly, hepatitis C virus (HCV), another common pathogen causing hepatitis, induces NLRP3 activation through glycoproteins, resulting in ASC-SPECK formation and subsequent cell death via both caspase-1 and caspase-3 pathways." (PMID 38002346, 2023). "In this regard, recent studies indeed demonstrated that in addition to classical inflammatory cytokines such as IL-1β and IL-18, HMGB1 released during NLRP3 inflammasome activation is also importantly implicated in both liver steatosis and subsequent hepatitis or fibrosis." (PMID 30140364, 2018). "Moreover, viral infected animals in deficiencies of NLRP3 and Caspase-1, two essential components of the inflammasome complex, also have reduced IL-1β induction along with ameliorated hepatitis." (PMID 26367131, 2015). "In the livers of ConA‐induced hepatitis mice, the expression levels of NLRP3, CASP1, and IL1B are significantly upregulated." (PMID 41503678, 2026). "Resveratrol alleviates heat stress–induced liver inflammation in broilers by modulating autophagy and suppressing NLRP3 inflammasome activation, and improves the production performance of heat‐stressed poultry." (PMID 41356228, 2025). "Purple sweet potato polysaccharide significantly improves Con A-induced hepatitis by regulating the P2X7R/NLRP3 pathway and reducing oxidative stress." (PMID 39917567, 2025). "RhIL-1RAs reduce the severity of ConA-induced hepatitis by eliminating ROS, inhibiting NLRP3 inflammasome assembly and activation, preventing pyroptosis, and competing with IL-1β." (PMID 39917567, 2025). "NLRP3 inflammasome activation induces the secretion of cytokines such as IL1β, which plays a role in inducing liver inflammation and fibrosis." (PMID 40089787, 2025). "Cd can activate the NLRP3 inflammasome, promoting liver inflammation and hepatitis, particularly severe during early estrus, by increasing TNF-α, MCP-1, and pro-inflammatory cytokines such as IL-1α, IL-1β, and IL-18." (PMID 39255638, 2024). "Previous studies have reported that TIL attenuates high-fat, high-carbohydrate (HFHC)-induced liver inflammation by inhibiting Nlrp3 inflammasome activation." (PMID 39388398, 2024). "The data show that the expression of NLRP3 inflammasomes in normal liver tissues is low, but it is upregulated in liver injury (i.e. hepatitis and cirrhosis)." (PMID 38182564, 2024). "Hepatitis B virus (HBV) has been identified as a major contributor to hepatitis through the activation of NLRP3 by HBV X protein, which is triggered by elevated levels of mitochondrial reactive oxygen species (mito-ROS)." (PMID 38002346, 2023). "In ConA-induced hepatitis, the expression of the NLRP3 inflammasome and the levels of activated caspase-1, IL-1β, and lactate dehydrogenase are elevated in the blood." (PMID 36969233, 2023). "Over-expression of NLRP3 inflammasome and cleaved levels of caspase-1 were reported in Concanavalin A (ConA)-induced hepatitis animal model." (PMID 38026692, 2023).
Hepatitis (continued). "Another important implication of the present study is that inhibition of XBP1/NLRP3 inflammasome contributes to MSCs-mediated immunomodulation in APAP-induced liver inflammation." (PMID 35842731, 2022). "In carbon-tetrachloride induced liver inflammation, neutrophils reprogrammed macrophages via microRNA miR-223, which downregulated NLRP3 inflammasome activity." (PMID 36552840, 2022). "In viral infectious hepatitis, excessive activation of the ROS/NLRP3/IL-1β axis resulted in aggravation of hepatitis." (PMID 35136014, 2022). "Our findings demonstrate the unexpected role of myeloid Notch1 signaling-induced Snail activation in negatively modulating the NLRP3-mediated innate immune response during IR-triggered liver inflammation." (PMID 31673056, 2020). "Our results highlight the importance of JAG1-mediated myeloid Notch1/HSF1/Snail signaling as a key regulator of NLRP3 activation and cell apoptosis during IR stress-mediated liver inflammation." (PMID 31673056, 2020). "We demonstrate that myeloid Notch1 signaling promotes heat shock transcription factor 1 (HSF1) and Snail activation, which in turn controls NLRP3-mediated innate immunity during IR-triggered liver inflammation." (PMID 31673056, 2020). "It provides insights into the anti-inflammatory mechanism of H2S and the novel H2S-related anti-inflammatory drugs targeting NLRP3 inflammasome, which can be designed and applied for the treatment of hepatitis in the future." (PMID 31315822, 2019). "Previous studies have indicated the involvement of NLRP3 inflammasome in the development of ConA-induced hepatitis." (PMID 29692782, 2018). "Strikingly, NLRP3−/− and caspase-1−/− mice were broadly protected from hepatitis as determined by decreased histological liver injury, serum aminotransferase (ALT)/aspartate transaminase levels, and pyroptosis." (PMID 29692782, 2018). "In summary, our results identified NLRP3 inflammasome and IL-1β as central mediators in the pathogenesis of ConA-induced hepatitis." (PMID 29692782, 2018). "All these results indicated that rhIL-1Ra was beneficial to inhibit NLRP3 inflammasome activation apart from blocking the effects of IL-1β in ConA-induced hepatitis." (PMID 29692782, 2018). "In the present study, we explored the effect of IL-1β in ConA-induced hepatitis, particularly the mechanism of its activation, which was dependent on NLRP3 inflammasome." (PMID 29692782, 2018). "Recent studies have indicated that the NLRP3 inflammasome drives pathogenesis of ConA-induced hepatitis." (PMID 30213101, 2018). "Scavenging of ROS by N-acetyl-cysteine also attenuated NLRP3 inflammasome activation and liver inflammation, indicating that the essential role of ROS in mediating NLRP3 inflammasome activation in ConA-induced hepatitis." (PMID 29692782, 2018). "The critical role of IL-1β/NLRP3 in the pathogenesis of ConA-induced hepatitis was also supported by an intervention study using an IL-1R antagonist that suppressed hepatic inflammation by diminishing ROS production and NLRP3 inflammasome activation." (PMID 30213101, 2018). "In summary, our data indicated that NLRP3 inflammasome activation and IL-1β production, as well as pyroptosis strongly increased in ConA-induced hepatitis." (PMID 29692782, 2018). "In addition, the concanavalin A (ConA)‐induced murine hepatitis model exhibits aberrant NLRP3 inflammasome activation, whereas relevant research in patients with AIH remains limited." (PMID 41503678, 2026). "Furthermore, the expression of inflammasome components, such as NLRP3 and IL-1β, was positively correlated with the HBV DNA load, suggesting the involvement of the NLRP3 inflammasome pathway in the progression of HBV-related hepatitis." (PMID 40688353, 2025). "Notably, accumulating evidence supported that the activation of aberrant NLRP3 inflammasome plays a pivotal role in MASH-related liver inflammation and fibrosis." (PMID 38977508, 2024).
Hepatitis (continued). "Intriguingly, miR-223-3p had been reported in several studies that it could regulate the inflammatory diseases such as hepatitis, neuritis, and intestinal inflammation by targeting the NLRP3 3’UTR region." (PMID 38448875, 2024). "In the same Con-A murine model of AIH, anti-rhIL1R (an antibody against the IL1 receptor) protects mice from hepatitis by inhibiting the effects of IL-1β, such as immune cell infiltration and the activation of the NLRP3 inflammasome via the elimination of ROS production." (PMID 38674122, 2024). "Furthermore, SIRT1 disruption or XBP1s overexpression in macrophages exacerbated APAP-triggered liver inflammation and augmented NLRP3/caspase-1 activity in MSC-administrated mice." (PMID 35842731, 2022). "Then, after SSd intervention, the expression of ROS in wild-type mice and αERKO mice decreased, mitochondrial membrane potential recovered, ATP level increased, NLRP3 inflammasome and fibrosis indexes decreased, liver enzyme levels decreased, and liver pathology showed liver inflammation." (PMID 35694250, 2022). "The arsenic-induced pyroptosis in NASH involved autophagy, CTSB, and the NLRP3 inflammasome cascade, and that taurine alleviated As2O3-induced liver inflammation by inhibiting the autophagic-CTSB-NLRP3 inflammasomal pathway rather than decreasing lipid accumulation." (PMID 36324154, 2022). "Given the ability for H2 to regulate NLRP3 activation, it is easy to imagine that the inhalation of the inert gas may act as a protective agent against hepatitis by inhibiting chronic inflammation in the liver." (PMID 34281264, 2021). "miR-223 has also been shown to disrupt NLRP3 inflammasome activity in a mouse model of hepatitis." (PMID 34026693, 2021). "First, we assessed whether NLRP3 inflammasome and IL-1β were activated in ConA-induced hepatitis, western blot was employed to observe protein expression of NLRP3 inflammasome and IL-1β." (PMID 29692782, 2018). "In ConA-induced hepatitis, lack of IL-33 was associated with increased hepatic IL-1β expression and more severe liver injury, however, a possible link between the NLRP3 inflammasome and IL-33 was not analyzed." (PMID 30213101, 2018). "In addition, the NLRP3 inflammasome plays a substantial role in ConA-induced hepatitis." (PMID 39917567, 2025). "NLRP3 inflammasome activates caspase 1 and promotes the maturation and secretion of downstream pro-inflammatory cytokines such as IL-1β and IL-18, resulting in the occurrence of programed cell death (apoptosis, autophagy, pyroptosis), liver inflammation and fibrosis." (PMID 37122694, 2023). "In addition, while the activation of the CB1R with an agonist promoted the expression and activation of the NLRP3 inflammasome in Kupffer cells, blocking CB1R with the antagonist AM281 reduced the expression of NLRP3, inflammasome activation, and liver inflammation." (PMID 36012687, 2022). "Notably, NLRP3 deficiency blocked LDH release and decreased the number of FAM-YVAD-FMK and PI double-positive cells in the livers, indicating that pyroptosis was present in mice with ConA-induced hepatitis and could be controlled by knocking out NLRP3." (PMID 29692782, 2018). "Moreover, NLRP3−/− and caspase-1−/− mice displayed downregulated IL-1β expression and diminished hepatitis, indicating that NLRP3 and caspase-1 were essentially required for IL-1β secretion and also contributed to the development of ConA-induced hepatitis in mice." (PMID 29692782, 2018). "Furthermore, recombinant human IL-1 receptor antagonists (rHIL-1RAs) alleviate liver inflammation and reduce NLRP3, caspase-1, and IL-1β production in hepatocytes by scavenging ROS and inhibiting pyroptosis, suggesting that the NLRP3 inflammasome may be a potential therapeutic target for AIH." (PMID 39917567, 2025).